GUCA1C (guanylate cyclase activator 1C)
Description:
Stimulates guanylyl cyclase 1 (GC1) and GC2 when free calcium ions concentration is low and inhibits guanylyl cyclases when free calcium ions concentration is elevated. This Ca(2+)-sensitive regulation of guanylyl cyclase (GC) is a key event in recovery of the dark state of rod photoreceptors following light exposure.
Synonyms: GCAP3
Tractability: No criterion of Open Targets' tractability assessment is met for any kind of drug.
Gene: Protein-coding gene on chromosome 3 (108,907,792 to 108,953,879, reverse strand). Ensembl gene ENSG00000138472.
Subcellular location (Human Protein Atlas): Focal adhesion sites
Pathways (Reactome):
Sensory Perception: Inactivation, recovery and regulation of the phototransduction cascade
Gene Ontology:
Molecular function: guanylate cyclase regulator activity; identical protein binding; protein binding; calcium ion binding; calcium sensitive guanylate cyclase activator activity
Biological process: cellular response to calcium ion; visual perception; regulation of signal transduction; signal transduction
Cellular component: photoreceptor outer segment membrane; photoreceptor disc membrane
Genetic constraint (gnomAD): Loss-of-function variants: 6 observed, 7.68 expected, observed/expected ratio (o/e) 0.78, 90% interval 0.43 to 1.51. That is too few expected variants to judge how well the gene tolerates losing a copy. Missense variants: 197 observed, 181.22 expected, observed/expected ratio (o/e) 1.09, 90% interval 0.97 to 1.22. Synonymous variants: 52 observed, 63.91 expected, observed/expected ratio (o/e) 0.81, 90% interval 0.65 to 1.02.
Homologues: Orthologues: chimpanzee GUCA1C (99% identical), macaque GUCA1C (94% identical), dog GUCA1C (78% identical), tropical clawed frog guca1c (58% identical), zebrafish guca1d (42% identical), zebrafish guca1c (40% identical), zebrafish guca1g (28% identical), Caenorhabditis elegans ncs-2 (28% identical), Drosophila melanogaster CG7646 (27% identical), zebrafish rcvrna (25% identical), zebrafish rcvrnb (23% identical), Drosophila melanogaster CG5890 (22% identical), and 7 more. Paralogues in human: GUCA1A (44% identical), GUCA1B (31% identical), HPCAL1 (31% identical), NCALD (30% identical), HPCA (29% identical), VSNL1 (27% identical), HPCAL4 (27% identical), NCS1 (27% identical), KCNIP2 (25% identical), RCVRN (25% identical), KCNIP1 (23% identical), KCNIP4 (22% identical), and 2 more.
Diseases named in the same sentence as GUCA1C in open-access papers:
GUCA1C is named in the same sentence as 8 diseases in open-access papers, as found by Europe PMC text mining. Sharing a sentence is not in itself a finding about the gene and the disease. The quoted sentences say what the papers report.
congenital glaucoma (2 papers, 2020 to 2022). "To further evaluate the role of GUCA1C LoF in congenital glaucoma and retinal physiology, we used zebrafish as an animal model." (PMID 32422965, 2020).
glaucoma (1 paper, 2020). Increased pressure in the eyeball due to obstruction of the outflow of aqueous humor. "One of the most interesting phenotypic findings in guca1c KO animals was the upregulation of GFAP in Müller cells, and the evidence of apoptosis in some ganglion, indicating the existence of gliosis and glaucoma-like alterations associated with GCAP3 LoF." (PMID 32422965, 2020). "The presence of GCAP3 in glaucoma-related human ocular tissues also supports the idea that functional disruption of GUCA1C plays a role in this disease." (PMID 32422965, 2020). "In an additional effort to evaluate the pathogenicity of GUCA1C LoF in glaucoma and retinal function, we analyzed the expression of this protein in the zebrafish eye and generated a guca1c KO zebrafish line using CRIPS/Cas9 genome editing." (PMID 32422965, 2020). "Based on these data, we hypothesize that the loss of GUCA1C function could result in decreased cGMP, increased IOP, and glaucoma." (PMID 32422965, 2020).
retinal disease (1 paper, 2022). "We also identified a subject carrying a point mutation in GUCA1C (ENST00000261047.8: c.301G > C) in heterozygous state, whose clinical phenotype is consistent with retinitis pigmentosa, thus suggesting the involvement of GCAP3 in inherited retinal disease." (PMID 35328663, 2022).
tumor (1 paper, 2021). "The CRX+/ARR3+/GUCA1C+ tumor population (clusters 1 and 4) was less unstable and consisted of two genomically different subpopulations." (PMID 34552068, 2021).
GUCA1C also shares sentences with these, for which no sentence is quoted: pancreatic cancer (1 paper); primary congenital glaucoma (1); retinal degeneration (1); retinitis pigmentosa (1).